EML4 (EMAP like 4)
Diseases named in the same sentence as EML4 in open-access papers (continued):
Sharing a sentence is not in itself a finding about the gene and the disease.
adenocarcinoma (75 papers, 2010 to 2025). A common cancer characterized by the presence of malignant glandular cells. "Cell and molecular analysis of the pleural fluid was positive for adenocarcinoma but FISH confirmed the loss of EML4-ALK inversion, respectively." (PMID 33546249, 2021). "Until now, among the 22 fusion partners, the most frequently identified concerned the EML4 protein (echinoderm microtubule-associated protein-like 4), which leads to the development of adenocarcinoma." (PMID 34572931, 2021). "Among all patients with adenocarcinoma, 10% had an epidermal growth factor receptor mutation and 3% had the echinoderm microtubule-associated protein-like 4–anaplastic lymphoma kinase (EML4-ALK) fusion gene." (PMID 29442281, 2018). "Aberrant ALK fusion gene is identified in 3 to 7% of NSCLC cases, mostly in adenocarcinoma, and the most common fusion is with the echinoderm microtubule-associated protein-like 4 (EML4)." (PMID 27078848, 2016). "Most patients with EGFR mutations presented as acinar predominant adenocarcinoma, while patients with EML4-ALK gene fusions tended to present as solid predominant adenocarcinoma." (PMID 26332764, 2015). "A significantly higher EML4-ALK fusion gene positivity rate was associated with adenocarcinomas (pooled OR = 2.53, 95% CI = 1.66–3.86, P<0.0001) and female (pooled OR = 0.61, 95% CI = 0.41–0.90, P = 0.01)." (PMID 25360721, 2014). "EML4‐ALK gene mutation results in different adenocarcinoma types." (PMID 37340599, 2023). "Histological transformation in EML4-ALK mutated NSCLC (adenocarcinoma)." (PMID 35456982, 2022). "In this study, sEVs were isolated from MPE fluid of four NSCLC patients, whose tumors were of adenocarcinoma histology and clinically validated to harbor EML4-ALK-fusion (PE002), KRAS-mutation (PE009), or mutations in the kinase domain of EGFR (PE011 and PE020)." (PMID 33671772, 2021). "Our meta-analysis confirmed that EML4-ALK is significantly associated with adenocarcinoma." (PMID 25360721, 2014). "K-RAS mutations appear in 25% of adenocarcinomas and may be a promising target of new therapeutic strategies, as well as the recently described EML4 protein and its EML4-ALK oncoprotein counterpart." (PMID 21811254, 2011). "These and 28 other mutations were detected at a significantly higher prevalence in adenocarcinoma cases including therapy-associated MET exon 14 skipping mutations (3.8% vs 0.8%), EML4-ALK fusions (2% vs 0%), and KIF5B-RET fusions (0.5% vs 0.1%)." (PMID 39664186, 2024). "In the adenocarcinoma group, the main mutations were ALK (Ile1461Val), in 95.24% of patients, EML4 (Lys398Arg) in 47.62% of the patients, and EGFR (Arg521Lys) and ROS (Arg167Gln) in 42.86% of the patients." (PMID 36422072, 2022). "Regarding the adenocarcinoma group, the main mutations were ALK (Ile1461Val) in 95.24% of patients, EML4 (Lys398Arg) in 47.62% of the patients, and EGFR (Arg521Lys) and ROS (Arg167Gln) in 42.86% of the patients." (PMID 36422072, 2022). "In patients with adenocarcinoma, the positive rate of EML4-ALK in tissue samples was 5.84% (58/994), and that in blood samples was 3.82% (10/262)." (PMID 32047559, 2020). "Adenocarcinoma (n = 95, 91.3%) was the dominant histology and 42 (40.4%) patients had targetable mutations (EGFR mutation – 37, EML4-ALK gene fusion – 5)." (PMID 32176106, 2020). "It is worth mentioning that their study was achieved in EGFR, K RAS, PI3KCA, HER2, and EML4-ALK wild-type adenocarcinoma only." (PMID 31781475, 2019). "In EGFR wild-type adenocarcinoma, the proportion of EML4-ALK translocation was 9.8% and predominant in patients younger than 65 years (14% versus 3.4%)." (PMID 27191886, 2016).
adenocarcinoma (continued). "Echinoderm microtubule-associated protein-like 4 (EML4)-ALK fusion proteins were recently detected in 3–5 % of NSCLC, particularly in adenocarcinomas." (PMID 26970967, 2016). "In Japanese patients, approximately 50 and 5% of adenocarcinomas have a mutation in the epidermal growth factor receptor (EGFR) and echinoderm microtubule-associated protein-like 4-anaplastic lymphoma kinase (EML4-ALK) fusion gene, respectively." (PMID 27070423, 2016). "Our analysis indicated that EML4-ALK-positive NSCLC comprised a unique subgroup of adenocarcinomas with distinct clinicopathological characteristics." (PMID 25706305, 2015). "Another therapeutic target, the echinoderm microtubule-associated protein like 4(EML4)-anaplastic lymphoma kinase (ALK) fusion protein, has also been uniquely detected in a subset of adenocarcinomas." (PMID 25977750, 2015). "Molecular biological analysis of the 93 patients with adenocarcinoma showed 59 epidermal growth factor receptor (EGFR) mutations (63.4%), five KRAS mutations (5.4%) and four EML4-ALK rearrangements (4.3%)." (PMID 25621070, 2015). "The other actionable mutation found in NSCLC is a translocation in echinoderm microtubule associated protein-like 4 – anaplastic lymphoma kinase (EML4–ALK) gene, which is found in approximately 4% of patients with adenocarcinoma." (PMID 25072026, 2014). "Previous studies have reported that EML4-ALK occurs at a significantly higher frequency in adenocarcinoma, while some studies have also reported that EML4-ALK occurs at a similar frequency in non-adenocarcinomas." (PMID 25360721, 2014). "The meta-analysis demonstrated that EML4-ALK translocation was predominant in female patients with adenocarcinoma." (PMID 23341890, 2013). "Our results suggest that the EML4-ALK translocation frequency differed in the adenocarcinoma group compared to the non-adenocarcinoma group (OR [95% CI] = 2.07 [1.11, 3.84], Z = 2.30; P<0.05)." (PMID 23341890, 2013). "The fusion product has oncogenic properties, and transgenic mice that express EML4-ALK in alveoli develop hundreds of nodules of adenocarcinoma." (PMID 22263108, 2012). "We report a 39-year-old patient diagnosed as adenocarcinoma harboring EGFR mutation and EML4-ALK fusion gene." (PMID 23181703, 2012). "Current estimates suggest that the EML4-ALK fusion is present in approximately 3–6 % of adenocarcinomas, depending upon on the population studied and the ALK detection methods used." (PMID 22825000, 2012). "From a histologic perspective, EML4-ALK rearrangement is seen almost exclusively in adenocarcinomas, and only rare cases have been reported in squamous cell carcinoma." (PMID 22263108, 2012). "The fusion gene has been observed predominantly in adenocarcinomas (∼1.5%) and is mutually exclusive with mutations in the EGFR, K-ras, and EML4-ALK genes." (PMID 22363766, 2012). "Eighteen EML4-ALK-positive patients had adenocarcinoma and one patient had mixed adenosquamous histology." (PMID 21504625, 2011). "Concurrent deletion in EGFR exon 19 and fusion of EML4-ALK was identified for the first time in a Chinese female patient with an adenocarcinoma." (PMID 20624322, 2010). "Other frequent mutations comprise EML4 inversion rearrangement with ALK generating EML4-ALK fusion oncogene that is found in 2–7% of NSCLC cases who are mainly non-smoker adenocarcinoma patients of a median age of 55 years." (PMID 39513892, 2024). "Though Eml4-Alk tumors are adenocarcinomas and thus consist primarily of epithelial cells, the distinct spindle-like labeling pattern of Z1 raised the possibility that Z1 might be cleaved by proteases expressed by non-epithelial cells of the TME." (PMID 36192379, 2022). "The EML4-ALK fusion gene is more common in adenocarcinoma than in other lung subtypes." (PMID 33425389, 2020). "This study shows that EML4-ALK rearrangement gene has high prevalence in selected adenocarcinoma and EGFR mutation-negative populations." (PMID 33425389, 2020).
adenocarcinoma (continued). "According to Paik’s report, EML4-ALK fusion gene-positive adenocarcinomas may metastasize to lymph nodes, and Vincent reported that EML4-ALK fusion gene-positive tumors tend to have lymph node and brain metastases." (PMID 25706305, 2015). "Therefore, we believe that clinical characteristics, such as smoking status, and adenocarcinoma, should be used to select patients for EML4-ALK fusion gene screening." (PMID 25706305, 2015). "We found a mucinous cribriform pattern in two of EML4-ALK-positive adenocarcinomas." (PMID 25407901, 2014). "In our study, none of the patients with EGFR mutation had an ALK gene rearrangement (data not shown), which is in line with the literature, indicating that EML4-ALK fusion tends to occur in adenocarcinomas lacking EGFR mutation." (PMID 23484153, 2013). "We confirmed that the EML4-ALK positive adenocarcinoma has no mutations in exons 18, 19, 20, 21 of EGFR gene (data not shown)." (PMID 23617234, 2013). "The SOE score for testing adenocarcinoma patients for the EML4-ALK translocation is ‘medium’." (PMID 22363766, 2012). "The SOE score for testing adenocarcinoma patients for the EML4-ALK translocation is ‘high’." (PMID 22363766, 2012). "Clinical characteristics associated with the EML4-ALK gene fusion are adenocarcinoma histology, never/light smoking history and younger age." (PMID 22825000, 2012). "Furthermore, translocation in the EML4-ALK gene has been described predominantly in adenocarcinomas." (PMID 21776344, 2011). "Among all patients with adenocarcinoma, patient had neither an epidermal growth factor receptor mutation and the echinoderm microtubule-associated protein-like 4-anaplastic lymphoma kinase (EML4-ALK) fusion gene." (PMID 30190787, 2018). "Studies on primary East Asian patient populations have detected the EML4‐ALK fusion gene in 3%–7% of NSCLCs,39, 40, 41, 42 most commonly in adenocarcinomas and females." (PMID 34599863, 2021). "The histopathological finding of the one case with EML4-ALK-V5p fusion is mixed papillary, solid (with signet ring cell) and acinar (cribriform pattern with mucin) adenocarcinoma." (PMID 34234236, 2021). "Eleven cases of EML4-ALK were scored positive; the positive rate was 3.70%, and the positive rate in adenocarcinoma was 3.82% (10/262)." (PMID 32047559, 2020). "EML4–ALK fusions occur in approximately 2%–5% of NSCLC cases, the majority of which are adenocarcinomas." (PMID 29764505, 2018). "SP-C-EML4-ALK transgenic mice possess EML4-ALK gene fusion specifically within the lung epithelial cells, resulting in rapid development of adenocarcinomas." (PMID 26064932, 2015). "We identified 15 studies that addressed the frequency of the EML4-ALK fusion gene in adenocarcinomas and non-adenocarcinomas." (PMID 25360721, 2014). "Adenocarcinomas exhibit distinct genomic changes that can be classified into clinically relevant molecular subsets according to KRAS, EGFR, and EML4-ALK status." (PMID 23341890, 2013). "Fusion and split FISH analyses using probes for EML4 and ALK genes confirmed that the adenocarcinoma of the right lung was indeed EML4-ALK positive." (PMID 23617234, 2013). "EML4–ALK fusions are most prevalent among young adenocarcinoma patients who are light or never smokers." (PMID 29764505, 2018). "Previous studies have reported that LC patients diagnosed with adenocarcinoma harboring EML4–ALK rearrangement tended to be younger and never or light smokers." (PMID 29844868, 2018). "A higher percentage of adenocarcinoma was found in patients harboring EML4‐ALK compared with double‐negative ones (90.8% vs. 80.2%; P = 0.026)." (PMID 28374971, 2017). "Our pooled analysis revealed that the EML4-ALK fusion gene was observed predominantly in adenocarcinoma, non-smoking and NSCLC patients, especially those diagnosed in the advanced clinical stage of NSCLC." (PMID 25706305, 2015).
adenocarcinoma (continued). "In Takamochi’s study, the proportion of lymph node involvement in EML4-ALK fusion gene-positive adenocarcinoma was significantly more frequent than in the negative counterpart." (PMID 25706305, 2015). "One adenocarcinoma was wild type for KRAS, EGFR and EML4-ALK genomic alterations." (PMID 25360587, 2014). "Some younger, non-smokers with adenocarcinomas are found to have an ALK/EML4 fusion oncogene which is currently a target for the drug Crizotinib." (PMID 24760004, 2014). "Some of previous investigators have identified EML4-ALK predominantly in young female non-smokers with adenocarcinoma, whereas other reports have identified this fusion gene in different populations." (PMID 25360721, 2014). "He identified 1 of 12 patients who had the EML4-ALK fusion gene and an EGFR mutation; the patient was a Chinese female non-smoker with a histologic adenocarcinoma." (PMID 25360721, 2014). "Since most patients with EML4-ALK fusions do not exhibit EGFR mutations, a specific molecular subset of adenocarcinomas is characterized by EML4-ALK fusion." (PMID 23341890, 2013). "The frequency of the EML4-ALK translocation among female non-smoking adenocarcinoma patients was 15.2% (5/33)." (PMID 23341890, 2013). "Nine reports (1413 cases) assessed the EML4-ALK translocation in adenocarcinoma and non-adenocarcinoma groups." (PMID 23341890, 2013). "In a subgroup of non-smokers with adenocarcinoma, EGFR was the most frequently altered gene, with a mutation rate of 49.8%, followed by EML4-ALK (9.3%), PTEN (9.1%), PIK3CA (5.2%), c-Met (4.8%), KRAS (4.5%), STK11 (2.7%), and BRAF (1.9%)." (PMID 22768234, 2012). "A high frequency of the EML4-ALK fusion gene was present in Chinese patients with NSCLC, particularly in patients with adenocarcinomas without EGFR/KRAS mutations." (PMID 20624322, 2010). "The EML4-ALK fusion gene was present at a high frequency in Chinese NSCLC patients, particularly in those with adenocarcinomas lacking EGFR/KRAS mutations." (PMID 20624322, 2010). "Grouping of patients revealed that the frequency of the EML4-ALK fusion was 16.13% (10/62) in patients with adenocarcinomas and 19.23% (10/52) in never-smokers." (PMID 20624322, 2010). "The EML4-ALK fusion was associated with non-smokers (P = 0.03), younger age of onset (P = 0.03), and adenocarcinomas without EGFR/KRAS mutations (P = 0.04)." (PMID 20624322, 2010). "Additionally, ALK fusion has been clinically observed in younger patients with adenocarcinoma with no or infrequent history of smoking; the most common type of fusion reported is EML4-ALK." (PMID 39513892, 2024). "Among those, the rearrangement between the Anaplastic lymphoma kinase (ALK) and the echinoderm microtubule-associated protein-like 4 (EML4) is identified in 3–7% of NSCLC cases, most commonly in younger patients, non-smokers, and those with adenocarcinoma histology." (PMID 34885137, 2021). "EML4-ALK fusion gene occurred around 3% of “non-smoker” adenocarcinomas of the lung." (PMID 23617234, 2013). "Further analysis indicated in the 32 cases of non-smoking, female, adenocarcinoma patients that the frequency of EGFR exon mutations and EML4-ALK translocation were 62.5%% (20/32) and 15.63% (5/32), respectively, which covers all 78.13% (25/32) of these patients." (PMID 23341890, 2013). "However, patients with EML4-ALK-positive NSCLC did not have exclusively adenocarcinoma histology in two other studies." (PMID 21504625, 2011). "Further analysis revealed that EML4-ALK was present at a frequency of 16.13% (10/62) in patients with adenocarcinomas, 19.23% (10/52) in never-smokers, and 42.80% (9/21) in patients with adenocarcinomas lacking EGFR and KRAS mutations." (PMID 20624322, 2010). "Notably, in a study, it was found that the preferential reactivity of p63 in TTF-1-positive adenocarcinoma was seen to have EML4-ALK translocation, implying that this expression might not be merely aberrant." (PMID 39070322, 2024).
adenocarcinoma (continued). "Approximately 60% of the tumors were adenocarcinoma, and 30% were the type of squamous cell, and there was 21 (17.5%) of 120 patients with some mutations for adenocarcinoma, which included 17 (14.2%) with EGFR mutations, and 4 (3.3%) with EML4-ALK rearrangements (detailed data were not presented)." (PMID 28602126, 2017). "Notably, the frequency of ALK fusions in patients with adenocarcinomas that did not exhibit EGFR/KRAS mutations reached 45.0% (9/21), strongly indicating that only a specific molecular subset of adenocarcinomas is characterized by EML4-ALK fusion." (PMID 20624322, 2010). "Compared with non-EML4-ALK-positive NSCLC, this group is significantly enriched for non-smoking patients with adenocarcinoma." (PMID 25706305, 2015). "Our results indicated that the EML4-ALK fusion gene occurred predominantly in non-smoking, adenocarcinoma patients, although no statistical difference was found between male and female patients." (PMID 25706305, 2015). "Certain clinicopathological characteristics of EML4-ALK-positive NSCLCs, including a young age at onset, lack of a smoking history and adenocarcinoma histology, are also observed in patients with NSCLC that harbours EGFR mutations." (PMID 25788996, 2015). "In summary, our meta-analysis demonstrated that the incidence of the EML4-ALK fusion gene was significantly higher in never or light smokers, women, patients with EGFR wild type and adenocarcinomas." (PMID 25360721, 2014). "The present meta-analysis of 17 studies, which included 4511 cases, revealed that the EML4-ALK fusion gene is highly correlated with a never/light smoking history, female and the pathologic type of adenocarcinoma, and is largely mutually exclusive of EGFR." (PMID 25360721, 2014). "The pooled frequency of EML4-ALK was 6.85% (158/2308) and 2.63% (26/990) in adenocarcinomas and non-adenocarcinomas, respectively." (PMID 25360721, 2014). "This meta-analysis revealed that the EML4-ALK fusion gene is highly correlated with a never/light smoking history, female and the pathologic type of adenocarcinoma, and is largely mutually exclusive of EGFR." (PMID 25360721, 2014). "Meta-analysis demonstrated that EML4-ALK translocation occurred in 4.84% (125/2580) of unselected patients with NSCLC, and was also predominant in non-smoking patients with adenocarcinoma." (PMID 23341890, 2013). "Further analysis proved that the incidence of EML4-ALK translocation in female, non-smoking, adenocarcinoma patients is as high as 15.2%." (PMID 23341890, 2013). "Taken together, EML4-ALK translocations were infrequent in the entire NSCLC patient population, but were frequent in the NSCLC subgroup of female, non-smoker, adenocarcinoma patients." (PMID 23341890, 2013). "Our results further indicate that the EML4-ALK translocation occurs predominantly in females, never-smokers, and adenocarcinoma patients." (PMID 23341890, 2013). "EML4-ALK translocations are infrequent in the entire NSCLC patient population, but are frequent in the NSCLC patient subgroup of female, non-smoking, adenocarcinoma patients." (PMID 23341890, 2013). "The incidence of EML4-ALK translocation in female, non-smoking adenocarcinoma patients was as high as 15.2% (5/33)." (PMID 23341890, 2013). "In summary, our real‐world study showed that patients harboring EML4‐ALK rearrangement tended to be younger at diagnosis, and more of them were nonsmokers and pathological diagnosed with adenocarcinoma compared with those without ALK rearrangement and EGFR mutation." (PMID 28374971, 2017).
lung (1 paper, 2024). "Furthermore, the immunoblot analysis showed that EML4-ALK v1 was present in NCI-H3122 pulmonary adenocarcinoma cells, and EML4-ALK v3a/b was present in NCI-H2228 pulmonary adenocarcinoma cells and PDT-LUAD#119 lung tumoroids." (PMID 38829559, 2024).